MIR548I4 (microRNA 548i-4)
Synonyms: hsa-mir-548i-4; MIR548I-4; MIRN548I4
Gene: MicroRNA gene on chromosome X (84,225,752 to 84,225,828, reverse strand). Ensembl gene ENSG00000221494.
Diseases named in the same sentence as MIR548I4 in open-access papers:
MIR548I4 is named in the same sentence as 1 disease in open-access papers, as found by Europe PMC text mining. Sharing a sentence is not in itself a finding about the gene and the disease.
MIR548I4 shares sentences with these, for which no sentence is quoted: tumor (1 paper).